MIR1273H (microRNA 1273h)
Synonyms: hsa-mir-1273h
Gene: MicroRNA gene on chromosome 16 (24,203,116 to 24,203,231, forward strand). Ensembl gene ENSG00000274466.
Homologues: Orthologues: chimpanzee MIR1273H (100% identical).